SYP (synaptophysin)
Diseases named in the same sentence as SYP in open-access papers (continued):
Sharing a sentence is not in itself a finding about the gene and the disease.
neuroendocrine carcinoma (57 papers, 2007 to 2026). A malignant neuroendocrine neoplasm composed of cells containing secretory granules that stain positive for NSE and chromogranin. "Neuroendocrine carcinoma are high-grade malignant neoplasms with cells that express little or no chromogranin A, somatostatin receptors, or hormones; however, high expression of INSM1 and synaptophysin has been observed in neuroendocrine carcinoma." (PMID 40491286, 2026). "The IHC Panel applied to our patient's histopathology sample also showed synaptophysin positivity and the microscopy also showed features suggestive of neuroendocrine cancer." (PMID 41179607, 2025). "Negative results were obtained for cytokeratin 20, CDX2, CD56, S100, and neuroendocrine markers such as synaptophysin, which excluded other tumor types, including neuroendocrine carcinoma and adenocarcinoma." (PMID 39860304, 2025). "CD56, chromogranin A, and synaptophysin are sensitive and specific markers for neuroendocrine cancers." (PMID 38974403, 2024). "Cases of neuroendocrine carcinoma (small cell carcinoma) were also identified on histology and further came out to be positive for synaptophysin and CD56 IHC." (PMID 39867094, 2024). "All of the patients were diagnosed as neuroendocrine carcinoma according to the immunohistochemical staining (IHC) of specific markers, including chromogranin A (CgA), synaptophysin (Syn), CD56, and Thyroid transcription factor-1 (TTF-1)." (PMID 37920164, 2023). "Biopsy results from a duodenal ulcer revealed poorly differentiated neuroendocrine carcinoma with positive synaptophysin and strong positivity of Ki-67, consistent with ESCC." (PMID 36779130, 2023). "In TUP, the diagnosis of neuroendocrine carcinoma was made with cytokeratin and synaptophysin positivity in tumors with histologically neuroendocrine features." (PMID 35308701, 2022). "We excluded the possibility of metastatic clear renal cell carcinoma, neuroendocrine carcinoma, perivascular epithelioid cell tumor, malignant melanoma, and sarcoma because of the negativity for vimentin, chromogranin, synaptophysin, and HMB45." (PMID 36140448, 2022). "MANECs are composed of variable adenocarcinoma components combined with morphologically distinct neuroendocrine carcinoma components, which are confirmed by synaptophysin immunohistochemistry, the gold standard marker of a neuroendocrine differentiation." (PMID 34680258, 2021). "Histopathological analysis disclosed the diagnosis of a neuroendocrine carcinoma of the right breast, with a significant positive immunostaining for chromogranin and synaptophysin by tumor cells." (PMID 32156307, 2020). "In this study the synaptophysin and CD 56 were found the most supportive immunomarkers for the diagnosis of poorly differentiated neuroendocrine carcinomas as compared to chromogranin." (PMID 32063972, 2020). "All (100%) identified patients with neuroendocrine carcinoma had synaptophysin expression >50% of tumor cells, while 30 tumors (69.8%) showed CgA expression." (PMID 28118820, 2017). "In thymic squamous cell carcinoma, positivity for biomarkers of neuroendocrine carcinoma, such as synaptophysin, neuron-specific enolase, chromogranin A and CD57, has been previously documented." (PMID 25146529, 2015). "Immunohistochemical examination revealed the concurrence of histologically proved neuroendocrine carcinoma (chromogranin A, synaptophysin, and CD56 were positive) and Stage II (T3, N0, and M0) according to the TNM staging classification of colorectal cancer." (PMID 24368955, 2013). "In our case, our patient stained positively for PAS, chymotrypsin, Chromogranin, and synaptophysin, indicative of tumor differentiation towards both acinar and neuroendocrine carcinomas." (PMID 24348574, 2013).
neuroendocrine carcinoma (continued). "The histological and immunohistochemical analyses revealed a well-differentiated neuroendocrine carcinoma involving ileum and pancreas, immunoreactive to CgA, synaptophysin, and CD56." (PMID 23009225, 2012). "A liver biopsy revealed metastatic tissue of neuroendocrine carcinoma (CgA+, synaptophysin+, NSE+, CD56+)." (PMID 23009225, 2012). "The lymph node metastases stained diffusely and strongly positive for synaptophysin and chromogranin A, consistent with the light microscopic classification of these as neuroendocrine carcinoma exclusively." (PMID 17988399, 2007). "Neuroendocrine carcinoma was the first impression, but positivity for synaptophysin, alpha-inhibin, transcription factor enhancer 3 (TFE-3), calretinin (focal), and CD56 (focal) and high Ki-67-labeling proliferating index (>80%) confirmed the diagnosis of ectopic ACC." (PMID 33815299, 2021). "Additionally, the expression levels of the neuroendocrine carcinoma markers synaptophysin (SYP) and chromogranin A (CGA) were concordant with those in the original tissue." (PMID 32092044, 2020). "Finally, there is a stochastic emergence of neuroendocrine cancers in the TRAMP model that is marked by increased expression of synaptophysin during tumor progression." (PMID 24586868, 2014). "Expression of chromogranin A, synaptophysin, and various other proteins involved in the formation of neurosecretory granules or CD 56, a neural cell adhesion molecule, can be used as markers of neuroendocrine differentiation, as in neuroendocrine carcinomas of other organs." (PMID 21436947, 2010). "The patient was first diagnosed with poorly differentiated neuroendocrine carcinoma based on tumor cell morphology and positivity to markers such as EMA, synaptophysin, and CD56." (PMID 40134582, 2025). "The histology showed gallbladder adenocarcinoma, with a single focus of neuroendocrine carcinoma (NEC) component of less than 30%; Ki-67 index > 80%, synaptophysin (Syn) (+), chromogranin A (CgA) (+), and clusters of differentiation (CD) 56 (+) (T2bN1M0, Stage IIIB)." (PMID 34767241, 2022). "Immunohistochemistry showed positive staining for synaptophysin (Syn), chromogranin A (CgA), CD56, and CK19, which are characteristics of neuroendocrine carcinoma." (PMID 36017024, 2022). "Neuroendocrine carcinoma (NEC) is a high‐grade neoplasm with pathological neuroendocrine features, such as expression of chromogranin A and synaptophysin." (PMID 31794158, 2020). "Lymphoma was excluded based on negativity for Leukocyte Common Antigen (LCA), CD20, and CD3, and three neuroendocrine markers (chromogranin, synaptophysin, neuron specific enolase [NSE]) were used to exclude a neuroendocrine carcinoma." (PMID 31205468, 2019). "Neuroendocrine proteins including CgA, S-100B protein, synaptophysin, GFAP protein, and neurofilaments, typically located in neural tissues, are commonly used as markers for neuroendocrine carcinomas." (PMID 31263455, 2019). "Neuroendocrine carcinomas are characterized by nuclear heteromorphism and frequent mitosis, and a clear positivity for NSE, CD56, CgA and synaptophysin." (PMID 24932236, 2014). "The lack of synaptophysin expression effectively excludes a neuroendocrine carcinoma, along with the absence of PAX8, which renders primary carcinomas of the thyroid, kidney, or ovaries unlikely." (PMID 41584573, 2025). "Notably, neuroendocrine cancer-related markers were significantly upregulated after SCLC transformation, such as SYP, CHGA, INSM1, etc.." (PMID 40437627, 2025). "Additionally, the neuroendocrine chromogranin A and synaptophysin markers were diffusely expressed in C1022 primary tumor and PDX, supporting the diagnosis of poorly differentiated neuroendocrine carcinoma." (PMID 37305585, 2023). "Of note, ERG was not expressed in the C1022 human tumor and PDX neuroendocrine carcinoma, however a strong expression of synaptophysin and chromogranin was measured confirming the NE phenotype." (PMID 37305585, 2023).
neuroendocrine carcinoma (continued). "High-grade neuroendocrine carcinomas are positive for synaptophysin and chromogranin and are negative for CD-99." (PMID 34722090, 2021). "The morphology of NUT carcinoma can often mimic neuroendocrine carcinoma; however, neuroendocrine markers are predominantly negative, with variable patchy positivity for synaptophysin and CD56 being described." (PMID 33351171, 2021). "In the present case, synaptophysin and chromogranin were positive while S-100 was negative which favoured the diagnosis of neuroendocrine carcinoma over olfactory neuroblastoma." (PMID 23476846, 2013). "The majority of the tumor was a high-grade neuroendocrine carcinoma with features of a small cell carcinoma that was positive for chromogranin, synaptophysin, and cytokeratin 19 and negative for hepatocellular antigen and alpha-fetoprotein (AFP)." (PMID 29147223, 2011). "Focal or aberrant staining for synaptophysin, chromogranin A, CD56 or INSM1 may occur in otherwise conventional gynecologic carcinomas, whereas true poorly differentiated neuroendocrine carcinomas represent aggressive tumors with distinct prognostic and therapeutic implications." (PMID 42196939, 2026). "The histological examination of the biopsy showed the presence of poorly differentiated neuroendocrine carcinoma (NEC), whose immunophenotype was reported as CK 19+, CK7−, CK20−, CDX2+, synaptophysin+, Ki67 90%." (PMID 40141766, 2025). "Neuroendocrine markers, such as synaptophysin and CD56, were positive, and neuroendocrine carcinoma (NEC) was considered a differential diagnosis." (PMID 39439633, 2024). "Interestingly, while 7/50 (14%) neu-like cases have morphology and phenotype consistent with neuroendocrine carcinoma (synaptophysin+, chromogranin+, not shown), the majority of cases harbor the usual urothelial carcinoma differentiation (43/50, 86%)." (PMID 35805028, 2022). "Pathology revealed a neuroendocrine carcinoma (NEC) that was positive for synaptophysin and CEA, with a Ki-67 index of 30%, and negative for chromogranin A and CD56." (PMID 39262550, 2024). "Moreover, CGA and SYP might be partially or totally absent in highly proliferative neuroendocrine carcinomas, making the diagnosis particularly challenging on small biopsies of metastatic lesions with unknown location of the primary tumor." (PMID 34571751, 2021). "Neuroendocrine cancer is immunohistochemically negative for AR and positive for chromogranin A, NSE, synaptophysin, CD56 and other markers." (PMID 38305451, 2024). "However, although the mutational spectra were suggestive in this regard, conventional morphology and immunohistochemical analysis against synaptophysin and CD56 did not provide sufficient evidence for a large cell neuroendocrine carcinoma component." (PMID 27105513, 2016).
small cell carcinoma (56 papers, 2005 to 2026). A neuroendocrine carcinoma composed of small malignant cells which are often said to resemble "oat cells" under the microscope. "On immunostaining, a p16-negative reaction was noted, but the specimen was partially positive for synaptophysin, suggesting small cell neuroendocrine carcinoma." (PMID 39896229, 2025). "Disease progression occurred after 12.5 months, and repeat lung biopsy revealed small cell carcinoma (TTF-1+/synaptophysin+/INSM1+; Ki-67 85%)." (PMID 41256964, 2025). "All the small-cell carcinoma cases were stained with synaptophysin, a specific neuroendocrine marker." (PMID 39070322, 2024). "In one patient, a cytological diagnosis including IHC revealed the presence of a small cell carcinoma with expression of synaptophysin." (PMID 38730611, 2024). "Immunohistochemical examination showed tumor cells positive for CD56 and synaptophysin, indicating small-cell neuroendocrine carcinoma." (PMID 39185439, 2024). "Neuroendocrine malignancies, such as small cell carcinoma, are characterised by distinctive biomarkers, including chromogranin A (CgA) and synaptophysin." (PMID 38149143, 2023). "Chromogranin A, CD56, and synaptophysin are immunohistochemical markers that are useful in the diagnosis and a low Ki-67 proliferation index (<1%) facilitates differentiation from small-cell carcinoma." (PMID 35685600, 2022). "Tumor cells were weakly positive for synaptophysin and showed a 95% Ki-67 index; therefore, small-cell carcinoma with some large cells was more likely." (PMID 36033527, 2022). "Biopsy was done and the pathology confirmed small cell carcinoma, strongly positive for cytokeratin (AE1/AE3) and insulinoma-associated protein 1 (INSM-1), scatteredly positive for chromogranin A, synaptophysin and CD56." (PMID 34477164, 2021). "Small-cell carcinomas and high-grade squamous cell carcinomas must be, due to the different clinical features, differentiated by neuroendocrine markers (synaptophysin/chromogranin A) and a squamous-basal marker (e.g., p40) expression." (PMID 32556556, 2021). "Immunohistochemical staining was positive for synaptophysin and chromogranin, with features similar to the small cell carcinoma component of the tumour in the prior oesophagectomy specimen." (PMID 31060613, 2019). "Liver biopsy identified epithelioid malignancy with Ki proliferation index 98% and immunohistochemical staining positive for synaptophysin and neuron-specific enolase, compatible with high-grade small cell carcinoma." (PMID 29755405, 2018). "The green part showed a grade III hepatocellular carcinoma with an immunoreaction to Hep Par 1, glypican 3 and α-fetoprotein, whereas the white part exhibited a small cell carcinoma, as evidenced by expressions of chromogranin A and synaptophysin." (PMID 28834900, 2017). "Small cell neuroendocrine carcinomas are usually positive for chromogranin, synaptophysin, and neuron-specific enolase, and overlap highly with PNET." (PMID 26549660, 2015). "In the case of small cell carcinoma, immunoreactivity for CgA and synaptophysin was evident only focally." (PMID 24695372, 2014). "Chromogranin A, CD56 and synaptophysin are the most useful neuroendocrine immunohistochemical markers, and low levels of Ki-67 can help to distinguish neuroendocrine from small-cell carcinoma." (PMID 23760790, 2013). "The patient underwent surgery, and the pathological diagnosis was small cell carcinoma due to the presence of the typical features of small round cells with scant cytoplasm that were positive for synaptophysin and chromogranin A in the resected specimen." (PMID 24099520, 2013). "Immunohistochemically, small cell carcinoma was positive for cytokeratin and also positive for at least one of neuroendocrine markers (neuron-specific enolase, chromogranin, synaptophysin, and CD56)." (PMID 27933124, 2009).
small cell carcinoma (continued). "Immunohistochemical stains were performed and the tumor cells of the small cell carcinoma component were positive selectively for synaptophysin and chromogranin, whereas, the high-grade urothelial carcinoma stained selectively for CK7, and CK20." (PMID 16269089, 2005). "Immunohistochemical stains were performed on cell blocks and showed positive staining of the small cell carcinoma component only for synaptophysin." (PMID 16269089, 2005). "In the extirpated tissue, solid proliferation of bare nucleus-like cells with a high N/C ratio, which resembles a biopsy finding suggestive of small cell neuroendocrine carcinoma, was primarily observed on the cervical side, and slight synaptophysin expression was noted." (PMID 39896229, 2025). "The true incidence is probably underestimated, as it may occasionally be misdiagnosed as small cell carcinoma due to their similar morphology and occasional expression of neuroendocrine markers such as synaptophysin and chromogranin A." (PMID 40255709, 2025). "More prevalent entities such as large cell neuroendocrine carcinoma and small cell carcinoma may initially elicit misdiagnosis due to crush artifacts and tissue necrosis, along with the expression of synaptophysin and a high ki-67 index." (PMID 38265099, 2024). "Positivity for synaptophysin or chromogranin is useful for identification of small cell carcinoma." (PMID 31103034, 2019). "Furthermore, chromogranin A, CD56, and synaptophysin, are immunohistochemical markers typically expressed in small cell neuroendocrine carcinomas of the lung." (PMID 23536778, 2013). "Both rhabdomyosarcoma and small cell carcinoma could be positive for synaptophysin, a potential pitfall to avoid." (PMID 21762516, 2011). "Furthermore, LNCaP with FOXA2 OE grew xenograft tumors much more rapidly than the control cells, showing mixed adenocarcinoma to small-cell carcinoma histology and strong synaptophysin (SYP) staining that closely recapitulated treatment-induced NEPC in patients." (PMID 40691407, 2025). "Therefore, the phenotype of Merkel cell carcinomas is CK7−/CK20+ (“dot-like”), CDX2−, SATB2+, Chromogranin+, Synaptophysin+ and positive for Merkel cell polyomavirus (MCPyV), while the phenotype of small cell carcinomas of the salivary glands is Synaptophin+, Chromogranin+/−, CD56+ and CDX2−." (PMID 29621151, 2018). "Whereas lymphoma, rhabdomyosarcoma, small cell carcinoma, desmoplastic small round cell tumor and neuroblastoma were excluded by negative staining for cytokeratin, CD20, CD3, desmin, myogenin, synaptophysin and chromogranin A." (PMID 40950824, 2025). "The tumor cells were positive for synaptophysin and CD56 with a Ki67 labeling index of 95% and were diagnosed as small cell neuroendocrine carcinoma (SCNEC)." (PMID 38787529, 2024). "The tumor cells were positive for synaptophysin and CD56 with a Ki67 labeling index of 95%, and he was diagnosed with small cell neuroendocrine carcinoma." (PMID 38787529, 2024). "On immunohistochemical staining, the nests of small cell carcinoma were positive for cytokeratin AE1/3 and cytoplasmic staining for the neuroendocrine marker synaptophysin." (PMID 31060613, 2019). "The pathological type of the present case was oat cell carcinoma and the tumor cells were immunoreactive for pancytokeratin and CD56 and focally immunoreactive for synaptophysin and TTF-1." (PMID 26137338, 2015). "Histopathologic evaluation revealed poorly differentiated small cell carcinoma with a high proliferative index, positive staining for synaptophysin and CAM 5.2, and negative staining for chromogranin and CD45." (PMID 42291954, 2026). "Small cell carcinoma was ruled out because chromogranin, synaptophysin, and CD56 tests were negative." (PMID 41245941, 2025). "POU2F3-driven small cell carcinomas are biologically distinct, characterized by the absence of classic neuroendocrine lineage markers, including synaptophysin, chromogranin and INSM1 and the expression of tuft cell lineage markers." (PMID 40931642, 2025).